SAT1 (spermidine/spermine N1-acetyltransferase 1)
Description:
Enzyme which catalyzes the acetylation of polyamines. Substrate specificity: norspermidine = spermidine >> spermine > N(1)- acetylspermine. This highly regulated enzyme allows a fine attenuation of the intracellular concentration of polyamines. Also involved in the regulation of polyamine transport out of cells. Also acts on 1,3-diaminopropane and 1,5-diaminopentane.
Synonyms: SSAT; SSAT-1; SAT; DC21; KFSD; KFSDX
Tractability: Small molecule: a structure with a bound ligand is known; a high-quality ligand is known; it has a high-quality binding pocket. PROTAC: ubiquitination databases record sites on it; a small molecule that binds it is known.
Target class: Enzyme; Transferase
Gene: Protein-coding gene on chromosome X (23,783,173 to 23,786,210, forward strand). Ensembl gene ENSG00000130066.
Subcellular location: Cytoplasm, cytosol
Pathways (Reactome):
Metabolism: Interconversion of polyamines
Gene Ontology:
Molecular function: diamine N-acetyltransferase activity; identical protein binding; N-acetyltransferase activity; protein binding; spermidine binding; acyltransferase activity, transferring groups other than amino-acyl groups
Biological process: angiogenesis; polyamine biosynthetic process; polyamine metabolic process; putrescine catabolic process
Cellular component: cytosol
Gene-disease validity (ClinGen):
ClinGen rates the evidence that SAT1 causes each of these diseases.
pediatric systemic lupus erythematosus (X-linked): Limited.
Homologues: Orthologues: chimpanzee SAT1 (100% identical), macaque SAT1 (98% identical), pig SAT1 (98% identical), guinea pig SAT1 (98% identical), dog SAT1 (96% identical), mouse Sat1 (96% identical), rat Sat1 (96% identical), tropical clawed frog sat1 (83% identical), zebrafish sat1a.1 (78% identical), zebrafish sat1b (75% identical), zebrafish SAT1 (73% identical), Drosophila melanogaster CG4210 (31% identical), and 1 more. Paralogues in human: SATL1 (59% identical), SAT2 (44% identical).
Diseases named in the same sentence as SAT1 in open-access papers:
SAT1 is named in the same sentence as 130 diseases in open-access papers, as found by Europe PMC text mining. Sharing a sentence is not in itself a finding about the gene and the disease. The quoted sentences say what the papers report.
breast carcinoma (14 papers, 2011 to 2024). "Previous studies have shown that high levels of acetylated polyamines are found in breast cancer in association with a simultaneous increase in spermidine and spermine N1 acetyltransferase (SAT1) activity and decreased polyamine oxidase activity." (PMID 37046602, 2023). "Previous studies have suggested a potential role of SAT1 (Spermidine/Spermine N1‐acetyltransferase 1) in cancer, which needs to be further elucidated in breast cancer." (PMID 39073262, 2024). "In our previous research, a subset of SAT1‐labeled cells was identified in breast cancer metastases, however, very limited evidence of SAT1 regarding to breast cancer has been reported." (PMID 39073262, 2024). "N1-acetylspermidine is known to exist in a larger amount in tumor tissues, such as breast cancer and colorectal cancer, than in normal tissues due to an increase in the activity of spermidine/spermine N1-acetyltransferase (SAT1)." (PMID 33182594, 2020). "Then, the CytoTRACE analysis in GSE176078 cohort revealed that breast cancer cells with high SAT1 expressions have a higher prevalence of cancer cell stemness, which also implied that SAT1 may facilitate tumor progression." (PMID 39073262, 2024). "To confirm this, we first examined the presence of SAT1 in different molecular subtypes of breast cancer, and found that SAT1 was extremely abundant in TNBC, compared to ER/PR‐positive or HER2‐positive breast cancers." (PMID 39073262, 2024). "Elevated SAT1 and decreased levels of PAOX were previously demonstrated in breast cancer, creating a favorable environment for diacetylspermine production." (PMID 36207498, 2022). "The results revealed that breast cancer tissues exhibited lower expression levels of SAT1, ALOX5, ALOX12, ATF3, ATF4, GPX4 and NFE2L2 compared to normal tissues; conversely, higher expression levels of ALOX15, ALOXE3 and HO‐1 were observed in breast cancer tissues than in normal tissues." (PMID 38516826, 2024).
lung carcinoma (14 papers, 2019 to 2025). "Lnc ASMTL-AS1 binds to U2AF2, stabilizing SAT1 mRNA expression and promoting ferroptosis in lung cancer cells." (PMID 40191204, 2025). "For example, lnc ASMTL-AS1 binds to U2AF2, stabilizing SAT1 mRNA expression and promoting ferroptosis in lung cancer cells." (PMID 40191204, 2025). "Indomethacin increased the expression of SAT1 and the levels of SSAT in non‐small cell lung cancer (NSCLC) cell lines." (PMID 38924680, 2024). "It has been used on lung cancer cells showing that it is able to reduce cell growth in vitro and PAs biosynthesis and to induce SAT1 and SMOX activities supporting the feasibility of the approach." (PMID 36755974, 2023). "We have previously reported that indomethacin increased the mRNA levels of SAT1 and the SSAT-1 protein levels in H1299 and A549 lung cancer cells." (PMID 37759783, 2023). "Using this test, patients with breast or lung cancer exhibit an enhanced SAT1 activity." (PMID 34517343, 2021). "LncRNA ASMTL-AS1, which is down-regulated in lung cancer cells, can stimulate ferroptosis in lung cancer cells by binding to U2AF2 and stabilizing spermidine/spermine N1-acetyltransferase 1 (SAT1)." (PMID 37005430, 2023). "Overexpression of ASMTL-AS1 stabilizes spermidine/spermine N1-acetyltransferase 1 (SAT1) mRNA, retarding the growth of lung cancer along with ferroptosis." (PMID 35055115, 2022).
glioma (13 papers, 2012 to 2025). A benign or malignant brain and spinal cord tumor that arises from glial cells (astrocytes, oligodendrocytes, ependymal cells). "Increased expression of Sat1 at the mRNA and protein levels has been associated with immune cell infiltration and poor outcomes for patients with low-grade glioma." (PMID 39605920, 2024). "High expression of SAT1 has been demonstrated in glioma, driving poor outcomes, triple negative breast cancer progression, and ferroptosis in endometrial cancers." (PMID 40563693, 2025). "We then used the Single Cell Portal tool to determine that SAT1 was expressed not only on glioma cells, but also on immune cells." (PMID 35227235, 2022). "We used the HPA to examine the level of SAT1 protein expression in normal brain and glioma tissues." (PMID 35227235, 2022). "In addition, that work authenticated that activated T cells mediated glioma cell killing by impeding the inhibitory CD161–CLEC2D pathway, which highlights the CD161 receptor and SAT1 as a novel and potential immunological therapy targets for glioma." (PMID 35227235, 2022). "Furthermore, the predictive power of SAT1 was validated using an independent LGG cohort from the Chinese Glioma Genome Atlas (CGGA) data." (PMID 35227235, 2022). "Brett-Morris reported that SAT1 (spermidine/spermine-N1-acetyltransferase 1) promoted resistance to ionizing radiation (IR) in glioma that contributed to glioma cell radioresistance, and thus suggests that SAT1 may potentially be a therapeutic target to sensitize GBM to cancer therapies." (PMID 26521947, 2015). "Consistent with the changes in expression, patients with higher expression of LDHA, MIF, NAMPT, PGK1, SAT1, and PLOD2, and lower expression of ALDOC, ABAT, ADCY2, GALNT13, and PDE8B showed poorer survival rates in all glioma samples." (PMID 38989284, 2024). "Similar to the TCGA datasets, all 11 genes exhibited WHO grade-dependent expression in glioma samples, with 6 upregulated (LDHA, MIF, NAMPT, PGK1, SAT1, and PLOD2) and 5 downregulated genes (ALDOC, ABAT, ADCY2, GALNT13, and PDE8B)." (PMID 38989284, 2024). "SAT1 expression significantly correlated with infiltrating macrophages and CD8 + T cells in low-grade glioma." (PMID 37853432, 2023).
colon cancer (9 papers, 2003 to 2023). "In colon cancer cells, certain NSAIDs, such as sulindac, induce apoptosis and suppress carcinogenesis by activating the SAT1 gene transcriptionally." (PMID 37759783, 2023). "In colon cancer cells, the activation of the peroxisome proliferator-activated receptor-γ (PPAR-γ) is related to the increase in spermidine/spermine-N1-acetyltransferase-1 (SSAT-1), a key enzyme for polyamine degradation, and related to cell cycle arrest." (PMID 37759783, 2023).
colorectal cancer (8 papers, 2006 to 2023). A primary or metastatic malignant neoplasm that affects the colon or rectum. "Sulindac has been reported to induce SAT1 gene mediated chemo preventive affect in colorectal cancer in a COX independent mechanism." (PMID 31417867, 2019). "However, our study is the first to report the putative involvement of SAT1, SMOX, SRM, and RR M2 in colorectal cancer." (PMID 31417867, 2019).
COVID-19 (8 papers, 2020 to 2024). A disease caused by infection with severe acute respiratory syndrome coronavirus 2. "They identified neutrophils (IFITM2, IFITM1, H3-H3B, SAT1 and S100A8) and macrophage cluster-1 (CCL8, CCL3, CCL2, KLF6 and SPP1) as the main immune cell subsets associated with severe COVID-19 cases." (PMID 34109284, 2021). "As an ISG, SAT1 showed an overall expression pattern comparable to other ISGs in our in vitro and in vivo data except for ciliated lung cells from mucosal brushes of COVID-19 patients." (PMID 34155207, 2021). "Among the identified gene signatures, IFITM2, IFITM1, H3F3B, SAT1, and S100A8 gene signatures were highly associated with neutrophils, while CCL8, CCL3, CCL2, KLF6, and SPP1 were associated with macrophage cluster-1 in severe-COVID-19 patients." (PMID 33138195, 2020). "This suggests that in patients with COVID-19-induced ARDS, SAT1 is an essential factor contributing to ferroptosis." (PMID 39170609, 2024). "Other scRNA sequencing results also support the conclusion that SAT1 and TXN are elevated in severe COVID-19 patients." (PMID 39170609, 2024). "Utilizing violin plots, we observed that the alteration trends in the expression of hub genes within the validation dataset mirrored those in GSM172114, confirming the heightened expression of SAT1, MTF1, and TXN in the COVID-19-induced ARDS group." (PMID 39170609, 2024).
viral infection (8 papers, 2014 to 2025). "The introduction of amino acid mutations at position Gly-1111 → Arg and Gly-1112 → Arg in VP1 of cell culture-adapted SAT1/NAM/307/98 (vNAM(KRR)/SAT) is thought to correlate with the acquisition of the HS-utilizing ability for viral infection of WT-CHO cells." (PMID 25056022, 2014). "To further check if silencing of the SAT-1 gene could favor the HSV-1 infection, we transfected HCEs with a siRNA targeting SAT-1 and observed the effect on the viral infection." (PMID 36043789, 2022). "It is relevant to consider that MSC are usually resistant to viral infection due to their expression of interferon (IFN), and, subsequently, IFN-stimulated genes (ISGs) (such as IFI6, ISG15, SAT1, PMAIP1, p21/CDKN1A, and CCL2)." (PMID 33808241, 2021). "Diagnostic specificity of SAT1, SAT3 and SAT2 topotype VII rRT-PCR assays was revealed to be 100% when evaluated against 18 negative clinical samples and two mock viral infections." (PMID 36204292, 2022). "Interestingly, MSC are usually resistant to viral infection due to their expression of ISGs such as IFITM, IFI6, ISG15, SAT1, PMAIP1, p21/CDKN1A, and CCL2 that preempt viral infection." (PMID 33808241, 2021). "Interestingly, MSC are usually resistant to viral infection due to their expression of interferon (IFN) stimulated genes (ISG) such as IFITM (interferon-induced transmembrane family), IFI6, ISG15, SAT1, PMAIP1, p21/CDKN1A, and CCL2 that preempt viral infection." (PMID 32766251, 2020).
glioblastoma (7 papers, 2012 to 2024). The most malignant astrocytic tumor (WHO grade IV). "High SAT1 expression in glioblastoma cells is associated with resistance to chemotherapy and radiation." (PMID 39125742, 2024). "Spermidine/spermine N1-acetyltransferase 1 (SAT1) responsible for cell polyamine catabolism is overexpressed in glioblastoma multiforme (GB)." (PMID 36358597, 2022). "In this study, we prepared a lipid nanoparticle-based siRNA delivery system (LNP-siSAT1) to selectively knockdown (KD) SAT1 enzyme in a human glioblastoma cell line." (PMID 36358597, 2022). "In the present study, we took advantage of the fact that SAT1 is localized to the X chromosome, and using cells derived from a male glioblastoma patient meant that only a single locus needed to be edited." (PMID 33007045, 2020). "However, these experiments indicated that reduction in SAT1 expression increased the sensitivity to both chemotherapeutic agents and radiation in several representative glioblastoma lines." (PMID 39125742, 2024). "Consequently, these results suggest that combining inhibition of SAT1 with standard-of-care treatment in glioblastoma may be a strategy for increasing the responsiveness of this devastating tumor type." (PMID 39125742, 2024).
prostate carcinoma (7 papers, 2006 to 2025). A carcinoma that arises from epithelial cells of the prostate gland. "Enhanced expression of SAT1 is a biomarker of kidney ischemia-reperfusion damage, poor prognosis prostate cancer, and radioresistance in brain tumors." (PMID 34517343, 2021). "The drug N1, N11-bis(ethyl)norspermine (BENSpm), a SAT1 stabilizer that increases polyamine acetylation, was utilized to understand whether prostate cancer cell lines could more selectively be targeted by further destabilization of polyamine metabolism." (PMID 30552315, 2018).
depression (6 papers, 2009 to 2024). "The role of SAT1 in mental illness has been particularly well studied in major depression and suicide and is one of the most consistently implicated genes in these conditions." (PMID 31978055, 2020). "The top gene networks in both categories displayed similarities, as they included numerous signal transduction and transcription components of the mitogen-activated protein kinase pathway and other genes previously implicated in depression (CREB1, SAT1)." (PMID 20376317, 2010). "Overall, these findings suggest that depression/suicide may be at least partially influenced by reduced expression of SAT1 resulting in low brain levels of putrescine and/or high levels of spermidine/spermine." (PMID 31134828, 2019).
hepatoma (5 papers, 2016 to 2024). "We found that PPT1 and FTL were highly expressed in hepatocellular carcinoma cell lines, while DAB2 and SAT1 were highly expressed in human hepatocytes." (PMID 37693905, 2023). "Transcriptome analysis revealed that in Huh7.5 hepatoma cells, the expression of polyamine biosynthesis genes (SRM, SMS, and AMD) was increased, while in hepatocyte-like HepaRG cells, the expression of the SAT1 gene involved in the degradation of spermine and spermidine was increased." (PMID 37189460, 2023).
pancreatic cancer (5 papers, 2024 to 2025). "Furthermore, SAT1 knockdown caused a significant decrease in pancreatic tumor burden, and treatment with FOLFIRINOX further reduced the tumor growth kinetics." (PMID 38547055, 2024). "SAT1 expression was significantly upregulated in pancreatic cancer patient tissue RNA–seq data analysed from multiple publicly available databases 40,41." (PMID 38429478, 2024). "Collectively, these findings indicate that SAT1 modulates mitochondrial homeostasis, thereby regulating mitochondrial bioenergetics in pancreatic cancer cells." (PMID 38547055, 2024). "Taken together, our data identified MUC1 as a key regulator of polyamine metabolite levels in pancreatic cancer cells through SAT1 enzyme." (PMID 38547055, 2024). "Given the upregulation of SAT1 upon acetate treatment, we knocked down SAT1 in pancreatic cancer cells, which led to the abrogation of acetate-induced survival of cancer cells under acidosis." (PMID 38429478, 2024). "To investigate the therapeutic potential of SAT1-mediated molecular processes in pancreatic cancer, we utilized pentamidine, a pharmacological inhibitor of SAT1." (PMID 38547055, 2024). "SAT1 has a higher expression in pancreatic cancer compared to the normal pancreas." (PMID 40075699, 2025). "Furthermore, overexpression of SP1 in pancreatic cancer cells resulted in increased expression of SAT1, which was further enhanced upon acetate treatment under low-pH conditions." (PMID 38429478, 2024). "Given our hypothesis that MUC1-mediated enhanced pancreatic cancer proliferation is mediated through SAT1, we treated MUC1-depleted cells with N1-acetylspermidine, the product of SAT1." (PMID 38547055, 2024). "Hence, our data identify a critical role of SAT1 in mediating oncogenic crosstalk between tumour cells and stellate cells to regulate pancreatic tumour burden." (PMID 38429478, 2024). "Furthermore, stratification of survival data of patients with pancreatic cancer based on SAT1 expression showed a significantly lower overall survival in patients with high SAT1 expression (median survival, 498 days) as compared to patients with low SAT1 expression (median survival, 1,332 days)." (PMID 38429478, 2024). "To establish the oncogenic function of SAT1, we overexpressed SAT1 in T3M4 and PaTu-8902 pancreatic cancer cell lines, with lower basal SAT1 expression." (PMID 38547055, 2024). "Although the exact mechanism for SAT1-mediated pancreatic cancer progression has not been addressed in this Article, we postulate that SAT1-mediated polyamine homeostasis is critical for cancer cell growth." (PMID 38429478, 2024). "By utilizing organoid and orthotopic pancreatic cancer mouse models, we observed that targeting SAT1 with pentamidine improved the efficacy of FOLFIRINOX, suggesting that the combination may represent a promising therapeutic strategy against pancreatic cancer." (PMID 38547055, 2024). "To identify whether HIF-1α mediates the regulatory mechanism governing MUC1-mediated regulation of SAT1, we assessed the expression of HIF-1α in MUC1-depleted pancreatic cancer cell lines." (PMID 38547055, 2024).
Alzheimer disease (3 papers, 2019 to 2024). A progressive, neurodegenerative disease characterized by loss of function and death of nerve cells in several areas of the brain leading to loss of cognitive function such as memory and language. "An increasing number of studies have shown that SAT1 is involved in the ferroptosis process of different diseases such as Alzheimer’s disease, lung adenocarcinoma, and neuropathic pain." (PMID 39457099, 2024).
brain cancer (3 papers, 2016 to 2022). A primary or metastatic malignant neoplasm affecting the brain. "A link between tumor resistance to ionizing radiation and overexpression of SAT1 was recently reported in brain cancer." (PMID 27283903, 2016). "Recently, Spermidine/spermine N1-acetyltransferase 1 (SAT1), an enzyme involved in polyamine catabolism in cells, was identified to promote brain cancer cell migration, proliferation, and resistance towards radiation therapy." (PMID 36358597, 2022).